CRH (corticotropin releasing hormone)
Diseases named in the same sentence as CRH in open-access papers (continued):
Sharing a sentence is not in itself a finding about the gene and the disease.
Cushing syndrome (continued). "Δ = Delta, dex = dexamethasone, CRH = Corticotropin Realising Hormone, DDAVP = Desmopressin, CS = Cushing’s Syndrome, CD = Cushing’s Disease, pCS = pseudo-Cushing’s syndrome, ACS = Adrenal Cushing’s Syndrome, EAS = Ectopic ACTH Secretion, Se = Sensitivity, Sp = Specificity." (PMID 35616760, 2022). "In cases of advanced MTC with ectopic corticotropin-releasing hormone (CRH) and adrenocorticotropic hormone (ACTH) production leading to Cushing syndrome, the use of somatostatin analogues, especially when combined with interferon-alpha, improved diarrhea only transitorily in a few patients." (PMID 23514614, 2013). "Since pre-operative petrosal sinus sampling/CRH assays and post-operative CRH immunostaining are not routinely performed when pheochromocytoma-associated ACTH-dependent Cushing’s syndrome is suspected, some published cases could have been misclassified as ACTH-secreting instead of CRH-secreting." (PMID 27699708, 2017).
Obesity (28 papers, 2009 to 2026). Accumulation of substantial excess body fat. "We observed massive obesity and metabolic syndromes that starkly differ from other models of CRH signaling deficiencies." (PMID 38227343, 2024). "Chronic administration of exogenous CORT concomitant with high-fat diet (HFD) feeding did not cause further increases in fat mass and body weight, although obesity secondary to HFD feeding is associated with elevated blood CRH, ACTH, and CORT levels." (PMID 33837263, 2021). "The biological process of hormone response can help prevent obesity by promoting the production of hormones like corticotropin-releasing hormone (CRH)." (PMID 38674532, 2024). "We found that Crhf/f mice with putatively knocked out corticotropin-releasing hormone (CRH) via AAV-mediated expression of Cre recombinase in the PVN rapidly developed obesity and metabolic syndrome, which was an intriguing and unexpected finding." (PMID 38227343, 2024). "The differential impairment of the transcript levels of CRH and UCNs in PBMCs from overweight and obese children highlights their involvement in obesity-related metabolic and cellular stress." (PMID 35276788, 2022). "Studies focusing on the PVH CRH neurons have suggested an importance of the responsiveness of these neurons in HFD-induced obesity." (PMID 33826123, 2022). "We have recently reported the dysregulated plasma profile of UCNs, CRH, and spexin plasma levels in overweight and obese children compared with normal weight controls (In press, Obesity, 2021)." (PMID 35276788, 2022). "Functional enrichment analysis revealed that the major biological processes are the cellular response to corticotropin-releasing hormone stimulus, positive regulation of glucose import, and oxygen binding when obesity occurs." (PMID 32610475, 2020). "Although the role of CRH in obesity is very complex, studies demonstrate that the CRH system has anorectic and thermogenic roles." (PMID 32694970, 2020). "Linear regression was next used to evaluate associations of methylation levels in CRH, ICAM-1, and LINE-1 in relation to the three obesity-related outcomes." (PMID 28360946, 2017). "Three genes were chosen because they are important regulators of biological pathways involved in obesity: CRH (stress), ICAM-1 (inflammation), and LEP (appetite)." (PMID 28360946, 2017). "We hypothesize that the targeted disruption of corticotropin-releasing hormone (CRH) expression within the paraventricular hypothalamic nucleus (PVN) through intracranial AAV8-hSyn-Cre injection in adult animals may result in obesity and metabolic alterations." (PMID 38227343, 2024). "Obesity-induced hypothalamic resistance to glucocorticoid inhibition or higher CRH-responsivity to stress may explain these observations." (PMID 37708362, 2024). "Therefore, defective glutamatergic neurotransmission from PVH CRH neurons is also likely to play a role in the pathophysiology of obesity." (PMID 33837263, 2021). "Since working over 60 h a week and working condition such as manual work may be acted as a high-intensity physical activity which could cause a physical stress sufficient to increase CRH and ACTH secretion, we presume that association between shift work and obesity was increased in the group." (PMID 26705475, 2015). "Having observed the development of diabetes and obesity in the PVN Cre-injected Crhf/f mice, we sought to validate these findings as attributable to the depletion of hypothalamic CRH." (PMID 38227343, 2024). "Lentivirus-mediated overexpression of the constitutive active form of AMPK in corticotropin-releasing hormone (CRH) positive neurons in PVN leads to a food preference to a high carbohydrate diet over a HFD and obesity in mice." (PMID 30423881, 2018). "In the current study, maternal obesity and HFD-consumption interacted to increase PVN CRH mRNA expression after overnight food withdrawal." (PMID 19606226, 2009).
Obesity (continued). "PVN CRH was markedly increased in HFD-fed animals, and this was more pronounced in those from obese dams (P<0.05, HFD and interaction with maternal obesity)." (PMID 19606226, 2009). "Recent studies have suggested a defective neuron responsiveness in AgRP neurons and CRH neurons by HFD, which may play a critical role in diet-induced obesity." (PMID 33826123, 2022). "Furthermore, the activation of corticotropin-releasing hormone (CRH)-expressing neurons in the paraventricular nucleus of the hypothalamus (PVH) shifts the preference from a carbohydrate-rich diet to an HFD, and these neurons are involved in the development of HFD-induced obesity." (PMID 38137451, 2023). "Individuals with obesity showed higher HPA axis responsiveness than their non-obese counterparts in the dex/CRH test with statistical significance for cortisol 30 min after stimulation with CRH, as well as a higher adrenal sensitivity to ACTH as measured by a lower ACTH/cortisol ratio." (PMID 36358358, 2022). "In male individuals with obesity, ACTH measured in the post-CRH sample was higher than in male non-obesity controls (OB: 1.95 pmol/l vs. NO: 1.05 pmol/l, p = 0.024, Kruskal–Wallis test with Dunn’s multiple comparison correction, see Suppl." (PMID 36358358, 2022). "Overall, significant negative correlations were observed for UCN1 expression and obesity markers (BMI, percentile, body fat percentage, and cholesterol), for UCN3 and TNFα and NGAL, as well as for CRH and TNFα, RBP4, ZAG, and circulating UCN2 levels (p < 0.05)." (PMID 35276788, 2022).
Adrenal insufficiency (27 papers, 2014 to 2025). Insufficient production of steroid hormones (primarily cortisol) by the adrenal glands. "For example, A classic manifestation is tertiary adrenal insufficiency, resulting from deficient corticotropin-releasing hormone (CRH) secretion." (PMID 41573202, 2025). "The pathophysiology of hyponatremia in adrenal insufficiency has been well-described in the literature; cortisol deficiency causes increased corticotropin-releasing hormone (CRH) release from the hypothalamus, and CRH is an ADH secretagogue." (PMID 37700952, 2023). "Elevated ISP compresses the pituitary stalk, and together these factors interfere with the delivery of hypothalamic hormones—such as TRH, CRH, and GnRH—resulting in secondary hypothyroidism, adrenal insufficiency, or hypogonadism." (PMID 41480352, 2025). "In primary adrenal insufficiency, the reduced cortisol production by damagedadrenal glands leads to increased production of CRH, POMC (an ACTH precursor),and MSH." (PMID 41313191, 2025). "Excess cortisol secretion suppresses corticotropin releasing hormone and ACTH and causes atrophy of the contralateral adrenal gland, so adrenal insufficiency or post-operative hypocortisolism is a predictor of cure." (PMID 37274343, 2023). "Corticotropin-releasing hormone (CRH) test further differentiate secondary from tertiary adrenal insufficiency." (PMID 26322261, 2015). "Stimulation of the pituitary with corticotropin-releasing hormone (CRH), or corticorelin, can be used to test for both primary and secondary adrenal insufficiency through its stimulation of the release of ACTH from the pituitary." (PMID 26500680, 2015). "Thus, while the Synacthen test is indispensable for confirming adrenal insufficiency, the CRH test provides valuable mechanistic insight into the level of hypothalamic–pituitary axis dysfunction." (PMID 41189622, 2025). "In addition to the patient's clinical symptoms and laboratory results, the results from ACTH and corticotropin-releasing hormone stimulation tests were used to make a diagnosis of primary adrenal insufficiency." (PMID 29390437, 2017). "However, existing evidence suggests that this dysfunction occurs at a central level, likely due to corticotropin-releasing hormone (CRH) deficiency rather than a primary adrenal insufficiency." (PMID 38724880, 2024). "Adrenal insufficiency (AI) is due to either dysfunction of the adrenal gland (primary AI), deficient pituitary adrenocorticotrophic hormone (ACTH) secretion (secondary AI), or deficient hypothalamic corticotropin-releasing hormone (CRH) secretion (tertiary AI)." (PMID 35495001, 2022). "Moreover, patients with mu receptors polymorphism A118G would have more opioid endocrinopathy and more opioid suppression of neurons that release corticotropin releasing hormone (CRH) which would explain how opioids induced adrenal insufficiency in such individuals." (PMID 29279713, 2017). "The pathology result was consistent with the clinical observation of lack of secondary adrenal insufficiency after surgery, what spoke for ectopic CRH production." (PMID 40927294, 2025). "The insulin tolerance test (ITT) is a gold standard test assessing the hypothalamic-pituitary-adrenal axis, and the corticotropin-releasing hormone (CRH) test is useful for differentiating CAI into secondary (pituitary) and tertiary (hypothalamic) adrenal insufficiency." (PMID 35281581, 2022). "The diagnosis of tertiary GC-induced adrenal insufficiency is based on the patient's history (therapy with GCs), low plasma cortisol and ACTH levels near zero, and functional tests such as the corticotropin-releasing hormone (CRH) or ACTH stimulation test." (PMID 25608777, 2014). "Secondary adrenal insufficiency arises from inadequate adrenocorticotropic hormone (ACTH) production due to pituitary pathology, whereas tertiary adrenal insufficiency stems from hypothalamic dysfunction leading to insufficient corticotropin-releasing hormone (CRH) secretion." (PMID 39233957, 2024).
Adrenal insufficiency (continued). "GC-induced adrenal insufficiency has to be considered in all patients during GC tapering, since all exogenous GCs exert negative feedback on the HPA axis with consequent inhibition of CRH-ACTH function, ultimately leading to pituitary corticotroph and adrenocortical cell atrophy." (PMID 38758491, 2024).
Anorexia (23 papers, 2008 to 2025). Lack of desire to eat (loss of appetite). "IL-1β is implicated as a cytokine in the development of anorexia associated with chronic disease (most commonly cancer), probably mediated through elevated levels of corticotropin-releasing hormone, which inhibits food intake." (PMID 37762896, 2023). "Corticotropin-releasing hormone (CRH) can acutely induce anorexia, while NPY stimulates CRH secretion via Y1 receptors, counter-regulating its own effects." (PMID 39200687, 2024). "They found out that the intracerebroventricular injection of ghrelin induces a CRH-dependent activation of the hypothalamic-pituitary-adrenal axis resulting in corticosterone secretion and, eventually, hyperactivity and anorexia in chicks." (PMID 35002780, 2021). "Nociceptin is likely to have additional roles in feeding behavior, as its administration into the BNST prevents corticotropin-releasing hormone–induced stress and anorexia." (PMID 31557134, 2020). "Many animal studies show that central microinjections of CRH can lead to anorexia and increased motor activity that can be reversed by CRH antagonists." (PMID 30400050, 2019). "If both histamine and CRH promote anorexia, how is it that sleep deprivation consistently results in hyperphagia?" (PMID 27997552, 2016). "Some studies have suggested that CRH hypersecretion may also play a role in the pathophysiology of the disorder, as central injections of CRH in animals leads to anorexia and increased motor activity, which can be reversed by CRH antagonists." (PMID 36793059, 2023). "Even so, several reports point to CRH and cortisol as the main neuroendocrine signals of the HPI axis involved in stress-induced anorexia." (PMID 38260137, 2023). "That hypothesis is in agreement with studies showing that an incoming CRH is increasing PVN TRH mRNA levels, given that the blockade of CRH-R2 in the PVN attenuates TRH expression and the anorexia of DIA animals." (PMID 35545425, 2022).
irritable bowel syndrome (22 papers, 2012 to 2025). Irritable bowel syndrome (IBS) is a chronic functional condition of the lower gastrointestinal (GI) tract characterized by abdominal pain or discomfort and disordered bowel habit (diarrhea, constipation, or fluctuation between the two). "EA and MA have been demonstrated to reduce abnormal 5-hydroxytryptamine and corticotropin-releasing hormone concentrations in patients with irritable bowel syndrome." (PMID 39234040, 2024). "A total of 40 studies from the last 15 years studying irritable bowel syndrome, inflammatory bowel disease, endometriosis, enteritis, stress impact on gastrointestinal processes and exogenous CRH administration effects were included." (PMID 35275963, 2022). "For example, electro-acupuncture decreases the hypothalamic CRH levels to the control levels in an animal model of irritable bowel syndrome." (PMID 33919862, 2021). "An exaggerated F response to CRH as well as higher basal F levels has been reported for patients with irritable bowel syndrome." (PMID 29854038, 2018). "The effects produced by CRH are so prominent that CRH is now considered an ideal candidate for the treatment of irritable bowel syndrome (Martinez and Taché, 2006)." (PMID 28900385, 2017). "As such inflammatory bowel disease (IBD) and irritable bowel syndrome (IBS) were expected to be some of the disease models used in animal studies to examine the effectiveness of CRH antagonists." (PMID 35275963, 2022). "Although not addressed, they could also store and secrete corticotropin-releasing hormone, as has been recently identified in jejunal eosinophils in irritable bowel syndrome, also in association with clinical severity." (PMID 29599471, 2018). "Corticotropin-releasing hormone (CRH) plays an important role in the pathophysiology of irritable bowel syndrome (IBS) and regulates the stress response through two CRH receptors (R1 and R2)." (PMID 26808377, 2016). "Corticotropin-releasing hormone (CRH) acts mainly via the CRH receptor 1 (CRH-R1) and plays a crucial role in the stress-induced pathophysiology of irritable bowel syndrome (IBS)." (PMID 22957021, 2012).
pituitary adenoma (21 papers, 2010 to 2025). "In summary, our study indicated that lower IGF‐1 and CRH levels, as well as serum potassium and sodium levels and blood glucose levels, were potentially associated with postoperative delirium in pituitary adenoma patients treated by endoscope‐assisted transsphenoidal surgery." (PMID 37137534, 2023). "In our case, dynamic testing was compatible with an ACTH-producing pituitary adenoma, as CRH stimulation induced a significant increase in ACTH and cortisol." (PMID 36797716, 2023). "Incorporating the results of imaging studies improved the PPV further: the PPV for CD was 100% in patients with positive responses to the CRH and desmopressin tests who had MRI findings indicative of a pituitary adenoma." (PMID 37560300, 2023). "describe an MEN1 patient with CS and two pituitary adenomas, one a corticotrope microadenoma, as well as ectopic production of corticotropin-releasing hormone from a thymic NET." (PMID 37409236, 2023). "Most cases of CS are ACTH-dependent (80-85%), the causes of which include ACTH-secreting pituitary adenomas and ectopic ACTH or corticotropin-releasing hormone (CRH) secretion." (PMID 37560300, 2023). "Given this premise, we decided to evaluate POMC expression as well as CRH-R1 and glucocorticoid receptor expression in ACTH-secreting pituitary adenomas and their response to CRH and dexamethasone in vitro." (PMID 27220856, 2017). "Patients with an ACTH-secreting pituitary adenoma have at least a 2-to-1 central-to-peripheral gradient at baseline or a 3-to-1 central-to-peripheral gradient after stimulation with CRH." (PMID 25386368, 2014). "Conversely, some extra pituitary tumors can mimic pituitary location with preferential lateralized secretion, notably in patients with ectopic CRH secretion or in the presence of ectopic pituitary adenoma within the sphenoid sinus as it was observed in our case." (PMID 36797716, 2023). "In preclinical studies, pasireotide has shown significant inhibition of basal and stimulated ACTH release in human ACTH-secreting pituitary adenomas and in AtT-20 murine corticotroph tumor cells, as well as significant inhibition of corticotropin-releasing hormone (CRH)-induced ACTH release in rats." (PMID 20478050, 2010). "In this study, we retrospectively investigated the maximum secretory capacity of ACTH and GH in patients with pituitary adenomas who exhibited normal ACTH and GH secretion in response to CRH and growth hormone-releasing peptide-2 (GHRP-2) stimulation tests." (PMID 40277822, 2025). "In contrast, 68Ga-CRH PET imaging is specific to ACTH-secreting lesions and allows for both morphological and functional assessment of pituitary adenomas, while also allowing for detection of ectopic ACTH-secreting lesions elsewhere in the body." (PMID 37560300, 2023). "Stimulation with CRH can lead to increased 18F-FDG uptake, possibly leading to higher detection rates of pituitary adenoma in CD." (PMID 37109254, 2023). "68Ga- CRH PET/MRI in particular may provide a one-stop shop for functional and morphological assessment of pituitary adenomas." (PMID 37560300, 2023). "Biological testing comprising low dose dexamethasone suppression and CRH stimulation tests were indicative of pituitary Cushing’s disease, but comprehensive pituitary MRI did not reveal any pituitary adenoma." (PMID 36797716, 2023). "When MRI was negative or inconclusive, molecular imaging detected a pituitary adenoma in 100% (68Ga-DOTA-CRH), 67% (11C-Met and 68Ga-pentixafor), 22% (18F-FDG–PET after CRH stimulation), 17% (18F-FDG–PET) and 0 (13N-ammonia) patients." (PMID 37109254, 2023). "Recognizing that most corticotroph adenomas express CRH receptors (CRH-1R), Walia and colleagues observed that conjugation of 68Ga-DOTA to CRH (68Ga-CRH) yields a PET ligand with apparent high sensitivity and specificity for the detection of ACTH-secreting pituitary adenomas." (PMID 35666391, 2022).